ICAM1 (intercellular adhesion molecule 1)
Diseases named in the same sentence as ICAM1 in open-access papers (continued):
Sharing a sentence is not in itself a finding about the gene and the disease.
lysosomal disorders (2 papers, 2018 to 2020). "The Muro and Muzykantov groups have used targeted therapeutics to endothelial ICAM-1 in vitro and in vivo for treatment of lysosomal storage diseases, acute and chronic respiratory diseases, and other vascular diseases." (PMID 32326657, 2020). "Pathological factors such as oxidative stress, inflammation, and metabolic imbalance, which are characteristic of lysosomal disorders, are high up regulators of ICAM-1 expression." (PMID 29843371, 2018). "Intracellular adhesion molecule 1 (ICAM-1) is a transmembrane protein expressed on cells in lysosomal disorders." (PMID 29843371, 2018).
microcephaly (2 papers, 2015 to 2026). A congenital or acquired developmental disorder in which the circumference of the head is smaller than normal for the person's age and sex. "The risk of microcephaly was increased in newborns with hyperEPO+ISSI (ISSI defined by CRP, SAA, MPO, IL-6, TNF-α, TNF-R2, IL-8, MCP-1, ICAM-1, E-SEL, red), often more prominently than for ISSI alone." (PMID 25793991, 2015).
mucositis (2 papers, 2014 to 2020). Mucositis is inflammation and damage of the mucous membranes lining the mouth and other parts of the gastrointestinal (GI) tract. "No mucositis was observed in Group D. Comparisons of the expression of ICAM-1 were in agreement with the macroscopic data." (PMID 24706999, 2014).
neuritis (2 papers, 2014 to 2016). A neuropathy arising from inflammation of one or more nerves. "We had previously observed development of neuritis in ICAM-1-/-NOD mice to be associated with an increased production of pro-inflammatory IL-17." (PMID 27711247, 2016). "Also, the spontaneous neuritis in ICAM-1 deficient (ICAM-1-/-) NOD mice is experimentally difficult to utilize due to its highly variable onset." (PMID 25286182, 2014). "To circumvent these limitations, we adoptively transferred chronic neuritis from ICAM-1-/- NOD mice into immunodeficient hosts thus triggering neuritis with synchronized onset but at the same time clinically resembling aspects of human chronic inflammatory neuropathies." (PMID 25286182, 2014).
neuropathic pain (2 papers, 2016 to 2023). Chronic pain caused by damage to nerve fibers. "Notably, complement component 5a (C5a) and intercellular adhesion molecule-1 (ICAM-1) were found to be increased within sEVs from the serum of neuropathic pain, whereas they were decreased in the whole serum of neuropathic pain compared to controls." (PMID 37563666, 2023). "Of the 47 investigated proteins, 21 (cathepsin S, CCL2, CCL4, CCL16, CFIII, CXCL5, cystatin B, E-Selectin, Fas/TNFRSF6, follistatin, GDF-15, GH, ICAM1, IL8, KLK5, MMP2, MMP9, P-Selectin, sortilin, TIMP4 and VEGF) were detectable by multiplex SP-PLA in ≥ 95% of the neuropathic pain patient samples." (PMID 26914813, 2016).
papillary thyroid carcinoma (2 papers, 2023 to 2024). "Another study showed that ICAM1 was positively correlated with papillary carcinoma, but not with other types." (PMID 37274228, 2023).
Priapism (2 papers, 2018). A painful and harmful medical condition in which the erect penis doesn't return to its flaccid state, despite the absence of both physical and psychological stimulation, within four hours. "There was increase in ICAM-1 level in HbSS priapism patients compared to HbSS steady-state patients (p < 0.001)." (PMID 29690499, 2018). "We have previously reported a continuous rise in ICAM-1, VCAM-1, and E-selectin in HbSS patients with sub-phenotypes including priapism and leg ulcers at a tertiary hospital." (PMID 30577523, 2018).
prion disease (2 papers, 2020 to 2024). A transmissible disease that is caused by a protein that is able to induce abnormal folding of normal cellular proteins, leading to characteristic spongiform brain changes, which are associated with neuronal loss without an inflammatory response. "Our observation that Icam1 expression is upregulated to a greater degree at 140 dpi in CD44−/− mice compared to WT mice during prion disease would support the hypothesis that deficiency in CD44 may be compensated for by Icam1 activity." (PMID 38877012, 2024). "In WT mice Icam1 accumulation was observed with a similar heterogenic and astrocytic pattern to CD44 in targeted brain areas such as the hippocampus at the terminal stage of prion disease." (PMID 38877012, 2024). "However, this difference in Icam1+ immunostaining between CD44−/− and WT mice was not significant at the terminal stage of prion disease." (PMID 38877012, 2024).
pulmonary embolism (2 papers, 2016 to 2022). The obstruction of the pulmonary artery or one of its branches by an embolus, sometimes associated with infarction of the lung. "In addition, the tissue-type plasminogen activator (tPA) modified by ICAM-1 antibody effectively dissolved the fibrin micro embolism in the lung tissues of rats, reflecting the potential application of ICAM-1 targeting in the treatment of pulmonary embolism." (PMID 36110525, 2022).
radiation pneumonitis (2 papers, 2014 to 2020). Inflammation of the lung due to harmful effects of ionizing or non-ionizing radiation. "Furthermore, persistently elevated IL1a (interleukin 1 alpha) and IL6 (interleukin 6), ICAM 1 (intercellular adhesion molecule 1), SP-A (surfactant protein A) and SP-D (surfactant protein D) serum levels are predictive for the development of radiation pneumonitis." (PMID 33521012, 2020). "Hallahan and Virudachalam demonstrated the importance of IR-induced microvascular EC ICAM-1 expression by showing that an ICAM-1 antibody treatment and ICAM-1 knockout rendered mice resistant to radiation pneumonitis." (PMID 25518850, 2014).
Retinal (2 papers, 2013 to 2023). "Retinal IR injury upregulates both P-selectin and ICAM1 expression, presumably leading to increased leukocyte rolling and adhesion on the endothelial lumen." (PMID 24325836, 2013). "MSC-derived EVs also downregulate the expression of various inflammatory molecules, intercellular adhesion molecule 1 (ICAM1), VEGF-A, and monocyte chemoattractant protein 1 (MCP1) and therefore improve retinal injuries." (PMID 37240353, 2023).
retinopathy of prematurity (2 papers, 2014 to 2015). A bilateral retinopathy characterized by neovascularization, scarring, retinal detachment, and eventually blindness. "Indeed, the expression of leukocyte adhesion molecules such as ICAM-1 and VCAM-1 are increased in models of OIR, and chemoattractants such as RANTES are elevated in the vitreous fluid of children with retinopathy of prematurity." (PMID 26219952, 2015).
salivary gland inflammation (2 papers, 2020 to 2025). "According to our results, ICAM-1 showed a linear pattern of immunoreactivity at the luminal-apical pole of luminal cells in neoplastic duct-like structures resembling salivary ducts in sialadenitis." (PMID 33372636, 2020). "With the activation of VCAM1 and ICAM1, cultured SGF expressed two adhesion molecules that characterize activated immunofibroblasts which were described in mouse models of salivary gland inflammation and in inflamed human salivary gland tissues of patients with SjD." (PMID 40277884, 2025).
spondyloarthritis (2 papers, 2014 to 2026). "VCAM-1 may represent a more sensitive marker of endothelial activation than ICAM-1 in treated spondyloarthritis." (PMID 41928308, 2026).
status epilepticus (2 papers, 2021 to 2023). Status epilepticus is defined as a continuous seizure lasting more than 30 min, or two or more seizures without full recovery of consciousness between any of them. "Patients in status epilepticus also had increased serum levels of ICAM-1 and P-sel, although the study did not exclude patients with comorbidities which could affect levels of the examined proteins." (PMID 36766708, 2023).
Stillbirth (2 papers, 2023 to 2025). Death of the fetus in utero after at least 22 weeks of gestation. "Despite reduced STB, ICAM-1 remained upregulated in iPL cases, suggesting CHI presence, which has been associated with miscarriage and stillbirth risk." (PMID 40723370, 2025).
T cell acute lymphoblastic leukaemia (2 papers, 2019 to 2021). "Indeed, neutralising antibodies against the adhesion molecule ICAM-1 in T cell acute lymphoblastic leukaemia were shown to block the transfer of healthy mitochondria from MSCs, thereby causing an increase in chemotherapy-induced cancer cell death." (PMID 34373767, 2021). "It was previously proven that ICAM-1 is upregulated in both classical and tall-cell PTC, therefore it could be considered a biomarker of PTC progression." (PMID 31430969, 2019).
tendinopathy (2 papers, 2022 to 2024). "Both early and chronic stage tendinopathy tissues expressed markers of vascular endothelial activation (CD31 ICAM1 VCAM1) relative to healthy tendons." (PMID 38655164, 2022). "Furthermore, the involvement of MMPs, ICAM-1, signal transducer, and STAT3 has been reported in the pathogenesis of tendinopathy." (PMID 39012676, 2024).
Thromboembolism (2 papers, 2022 to 2023). The formation of a blood clot inside a blood vessel that subsequently travels through the blood stream from the site where it formed to another location in the body, generally leading to vascular occlusion at the distant site. "Thus, the local hemodynamic conditions of venous valvular reflux, thrombus resolution, and multiple biomarkers (ICAM-1, P-Selectin, and NETs) are involved in the process of thromboembolism and PTS." (PMID 38068502, 2023).
transient ischemic attack (2 papers, 2020 to 2024). A brief attack (from a few minutes to an hour) of cerebral dysfunction of vascular origin, with no persistent neurological deficit. "In patients with transient ischemic attack, ICAM-1 was higher in patients with increased IMT in the carotid arteries." (PMID 38672515, 2024).
upper respiratory tract infection (2 papers, 2004 to 2018). "Alternatively, upregulation of ICAM1 the primary ligand for rhinovirus could increase the susceptibility to, or severity of upper respiratory tract infection, resulting in upper airway oedema and/or adenoid hypertrophy." (PMID 15527500, 2004). "The antiviral effects of zinc (5 mg), through the Intercellular Adhesion Molecule 1 (ICAM-1) receptor blocking, have been considered as one of the most important actions for impacting on incidence and/or duration of upper respiratory tract infections (URTI)." (PMID 29853961, 2018).
uremia (2 papers, 2020 to 2026). A clinical syndrome associated with the retention of renal waste products or uremic toxins in the blood. "Thus paving the way also to the other newer FXa inhibitor, which recently demonstrated to affect VCAM-1 and ICAM-1 in uremia induced vascular dysfunction." (PMID 33301454, 2020). "Repeated bursts of such power activate endothelial NADPH-oxidase and NF-κB, up-regulating ICAM-1, VCAM-1, and pro-inflammatory cytokines; in uremia this cascade is amplified, further weakening the blood–brain barrier and permitting neurotoxic proteins and immune cells to invade the parenchyma." (PMID 41224909, 2026).
Varicose veins (2 papers, 2007 to 2025). Enlarged and tortuous veins. "Nevertheless, it has been reported that a significant increase in endothelial adhesion molecule ICAM-1, associated with more thromboxane A2 and prostaglandin E2 synthesis, and with an increased interaction among leukocytes, platelets and endothelial cells, is observed in varicose veins." (PMID 18949086, 2007). "Serum ICAM-1 levels in varicose veins did not significantly differ from systemic values and were unaffected by mesoglycan treatment." (PMID 40362286, 2025).
Zinc deficiency (2 papers, 2022 to 2025). A deficiency of the essential metal Zinc; an essential cofactor for many enzymes. "Similarly, in vitro studies have shown that Zinc deficiency results in increased IL‐6, IL‐1β production, and increased expression of intercellular adhesion molecule 1 that helps in leukocytes' extravasation." (PMID 36239436, 2022). "Zinc deficiency exacerbates these processes by upregulating molecules like vascular cell adhesion molecule-1 (VCAM-1) and intercellular adhesion molecule-1 (ICAM-1), facilitating monocyte attachment and intensifying vascular inflammation and AS progression." (PMID 40390089, 2025).
abdominal abscesses (1 paper, 2010). "Inhibiting the production of TNFα resulted in the reduction of intercellular adhesion molecule 1 (ICAM-1) on polymorphonuclear cells, which are key players in the formation of intra-abdominal abscesses." (PMID 21234388, 2010).
Acidosis (1 paper, 2011). Abnormal acid accumulation or depletion of base. "Acidosis/GPR4 stimulated the expression of ICAM-1, however, to a lesser extent as there was both a minor increase in HUVEC/Vector cells and an increase of 10-fold in HUVEC/GPR4 cells." (PMID 22110680, 2011).
adenoid cystic carcinoma (1 paper, 2012). A malignant tumor arising from the epithelial cells. "We performed immunohistochemical analysis on 132 primary adenoid cystic carcinoma and adjacent non-cancerous tissues using commercial EBP1, MMP9, E-cadherin and ICAM-1 antibodies." (PMID 23110497, 2012).
adenoma (1 paper, 2020). A neoplasm arising from the epithelium. "Regarding ICAM-1, strong correlation was noted between controls, adenomas and adenocarcinomas (p < 0.001)." (PMID 33372636, 2020). "Regarding ICAM-1, its expression was found increased in adenomas, with non-specific distribution in malignant SGTs and strong correlation between the histological subtypes and controls (p < 0.001)." (PMID 33372636, 2020).
adenovirus infections (1 paper, 2019). "Receptors can be widely available, such as in paramyxovirus (CD46 in measles and sialic acid in Sendai virus) and picornavirus infections (ICAM-1 in Coxsackie virus), or narrowly restricted in adenovirus infections (integrin on monocytes)." (PMID 30871070, 2019).
Ageusia (1 paper, 2025). A rare condition that is characterized by a complete loss of taste function of the tongue. "Anosmia/ageusia remain the main symptom associated with the more biomarkers with the more strength (IFNγ, IP-10, ICAM-1)." (PMID 40449327, 2025).
alcohol- (1 paper, 2020). "ACT and Sil failed to affect the hepatic levels of TPO, RBP4, IL-23, ICAM-1, NGAL, and VCAM-1 in acute alcohol-injured mice compared with the model group." (PMID 32719658, 2020).
alveolitis (1 paper, 2020). "The high expression of ICAM-1 helps to connect activated T cells and multinucleated leukocytes in the alveolar cavity and stimulate alveolitis." (PMID 33101446, 2020).
anaphylaxis (1 paper, 2023). An acute hypersensitivity reaction that occurs from exposure to an allergen. "Similarly, the six anaphylaxis patients with samples taken within 6 h of the hypersensitivity reaction demonstrated higher median (IQR) levels of anti-BNT162b2 IgG and IgM levels, C5a and ICAM-1 compared to the non-reactors." (PMID 37376409, 2023).
anxiety disorder (1 paper, 2019). A category of psychiatric disorders which are characterized by anxious feelings or fear often accompanied by physical symptoms associated with anxiety. "It will not discuss ICAM-1 in anxiety disorders because research on immune parameters in this disorder is rare and no studies have been published on ICAM-1 in anxiety disorders." (PMID 31824303, 2019).
aortic aneurysm (1 paper, 2023). A ruptured aneurysm located in the wall of the proximal portion of the descending aorta proceeding from the arch of the aorta. "Given the variety of chemokines upregulated within aortic aneurysms, it seems likely that IL8 and ICAM1 could interact to promote inflammatory cell infiltration." (PMID 37238945, 2023).
Arrhythmia (1 paper, 2021). Any cardiac rhythm other than the normal sinus rhythm. "MG could attenuate VCAM-1, ICAM-1, MCP-1, and MMP9, inhibit the proliferation of smooth muscle cells and fibroblasts, and obtain arrhythmia from I/R injury to show cardiovascular protection." (PMID 33815113, 2021).
artery dissection (1 paper, 2018). "In addition, ICAM-1 has been identified to be a risk factor for spontaneous cervical artery dissection." (PMID 29514135, 2018).
aspergillosis (1 paper, 2018). Aspergillosis is an infection, growth, or allergic response caused by the Aspergillus fungus. "Similarly, induction of IL-8 and ICAM-1 transcription in A549-moDC-co-cultures was decidedly stronger than in an aspergillosis bilayer model, indicative of a more robust induction of pro-inflammatory cascades including the NF-κB pathway." (PMID 30671036, 2018).
autism (1 paper, 2014). Persistent deficits in social interaction and communication and interaction as well as a markedly restricted repertoire of activity and interest as well as repetitive patterns of behavior. "For example, previous studies found that ICAM-1 was decreased in autism, although we showed that it was increased significantly in adult males with AS." (PMID 24467795, 2014).
autoimmune encephalitis (1 paper, 2011). Inflammation of the brain secondary to an immune response triggered by the body itself. "Recently, anti-ICAM-1 antibodies have been shown to positively affect the clinical course of experimental autoimmune encephalitis (EAE) when given in an early phase of the disease, whereas treatment given in a later phase, worsened the clinical score of the treated mice." (PMID 21589878, 2011).
autoimmune myocarditis (1 paper, 2023). Autoimmune myocarditis is an autoimmune disease that affects the heart. "Therefore, ETBR overexpression to alleviate autoimmune myocarditis may be associated with ICAM-1 downregulation." (PMID 37901475, 2023). "Hence, we hypothesized that ETBR overexpression may lead to inflammatory attenuation in experimental autoimmune myocarditis in rats, which is associated with the protective effect of ICAM-1 downregulation." (PMID 37901475, 2023). "Further studies are warranted to investigate the role of ICAM-1 in cardiac homing of CD4+ T lymphocytes during the pathological process of autoimmune myocarditis." (PMID 37901475, 2023). "CD4+ T lymphocyte homing is considered the initiating event in autoimmune myocarditis, which is highly dependent on ICAM-1." (PMID 37901475, 2023).
basal cell carcinoma (1 paper, 2016). A carcinoma involving the basal cells. "While there are not many studies on the effects of early life stress specifically on ICAM-1, basal cell carcinoma patients that were maltreated by their parents exhibited poor ICAM-1 responses." (PMID 34055816, 2016).
behavioral disorders (1 paper, 2023). "Since ICAM-1 represents an adhesion receptor that promotes leukocyte migration from circulation to inflammation site, our results may confirm the presence of inflammation in brain regions, possibly contributing to cognitive and behavioral disorders." (PMID 37064799, 2023).
bladder overactivity (1 paper, 2025). "Increased responsive proinflammatory mediators (NGF, ICAM-1, COX-2, IL-1β, IL-6, TNF-α) likely contribute to bladder overactivity." (PMID 39941129, 2025).
bladder tumor (1 paper, 2015). "All the bladder tumor cell lines analyzed expressed at least low amounts of ICAM-1 at the surface, suggesting that they all have what has been suggested as the minimal requirement for adhesion." (PMID 26106390, 2015).